BAK1 (BCL2 antagonist/killer 1)
Diseases named in the same sentence as BAK1 in open-access papers (continued):
Sharing a sentence is not in itself a finding about the gene and the disease.
Diverticular disease of (1 paper, 2024). "Remarkably, we detected significant associations between BAK1 and Rheumatoid arthritis/Polyarthropathies (p = 2.50e-3) as well as BCL2L2 and Diverticular disease of the intestine (p = 3.86e-02)." (PMID 38589365, 2024).
glaucoma (1 paper, 2021). Increased pressure in the eyeball due to obstruction of the outflow of aqueous humor.
head and neck cancer (1 paper, 2018). A primary or metastatic malignant neoplasm affecting the head and neck. "Conversely, one study investigating BAK1 in tumor and non-tumor lesions in matched head and neck cancer patients found that loss of BAK1 was associated with a non-tumor phenotype." (PMID 30404157, 2018).
hearing loss (1 paper, 2022). "Beyond BAK1 and BCL2, it is likely that additional genomic targets will be identified for evaluation as potential circulating biomarkers for hearing loss." (PMID 34957708, 2022).
Hepatitis B (1 paper, 2023). "For example, for Hepatitis B, CASP1 and BAK1 are ranked 1 (best) and 10, respectively." (PMID 36791052, 2023).
infertile (1 paper, 2023). "The gene expression analysis revealed significant changes in the endometrium regarding the genes associated with cell death (BAK1), epigenetic DNA modification (TET2) and the immune response (IL-6) which were upregulated in females with the diagnosed unexplained infertility." (PMID 37576599, 2023).
ischemia (1 paper, 2023). A hypoperfusion of the BLOOD through an organ or tissue caused by a PATHOLOGIC CONSTRICTION or obstruction of its BLOOD VESSELS, or an absence of BLOOD CIRCULATION.
microcephaly (1 paper, 2023). A congenital or acquired developmental disorder in which the circumference of the head is smaller than normal for the person's age and sex. "Cellular mechanistic studies show that this microcephaly results from either depletion of the progenitor pool by DNA damage-induced cell death, diminished neuron production caused by chromosome separation inhibition-induced mitotic delay or Bak1-induced apoptosis." (PMID 37612280, 2023).
myeloid neoplasm (1 paper, 2022). Proliferation of myeloid cells originating from a primitive stem cell. "It turned out that the level of Bak1 protein in all myeloid neoplasms and Daudi and Jurkat cells was similar to the level present in PBMCs." (PMID 35563410, 2022).
oral cancer (1 paper, 2023). "This study permitted the proposal of 8 salivary biomarkers for oral cancer in patients previously infected with HPV (RPRD2, PSCA, MCM2, CDKN2A, BAK1, HSPA1A, TANK, MAP2K1)." (PMID 37599356, 2023).
oral squamous cell carcinoma (1 paper, 2021). "BAK1 is associated with the development of oral squamous cell carcinoma and could serve as a prognostic biomarker in that malignancy." (PMID 34869345, 2021).
periodontitis (1 paper, 2019). An acute or chronic inflammatory process that affects the tissues that surround and support the teeth. "In conclusion, P. gingivalis HmuY protein might contribute to the survival of PBMC in periodontitis by regulating the transcriptional profile of genes involved in apoptosis, such as FASL, caspase 9, APAF1, FAS, TNFSF10 (TRAIL), and BAK1." (PMID 31011284, 2019).
preeclampsia (1 paper, 2023). Preeclampsia is a hypertensive disorder of pregnancy that is characterized by new-onset hypertension with proteinuria presenting after 20 weeks of gestation, and depending on mild or severe forms may initially present with severe headache, visual disturbances, and hyperreflexia. "In the current study, we determined a change of enhanced BAK1 expression in placenta tissue from both preeclampsia women and LPS-induced preeclampsia mice model, showing a more definite association between BAK1 and preeclampsia." (PMID 37507742, 2023). "Thus, further research is needed to verify the regulation role of the mTOR/ERK1/2 signaling/BAK1 axis in preeclampsia." (PMID 37507742, 2023). "However, few studies have been reported where BAK1 expression was directly detected in the placental tissue of preeclampsia." (PMID 37507742, 2023). "Hsa_circ_0002348 might be a novel regulator of trophoblast proliferation and apoptosis through miR-126-3p/BAK1 axis in preeclampsia, which may serve as a potential target for detecting and treating preeclampsia." (PMID 37507742, 2023). "Therefore, we inferred that BAK1 might be involved in regulating trophoblast apoptosis of preeclampsia mediated by hsa_circ_0002348/miR-126-3p axis through mTOR/ERK1/2 signaling." (PMID 37507742, 2023). "Additionally, little is known about the upstream regulatory networks of BAK1 in preeclampsia." (PMID 37507742, 2023).
psoriasis (1 paper, 2023). An autoimmune condition characterized by red, well-delineated plaques with silvery scales that are usually on the extensor surfaces and scalp. "Additionally, we identified 10 key genes including AIM2, BAK1 and CASP1, and confirmed the accuracy of these key genes in diagnosing psoriasis." (PMID 37861483, 2023).
spinal cord injury (1 paper, 2023). Penetrating and non-penetrating injuries to the spinal cord resulting from traumatic external forces (e.g., WOUNDS, GUNSHOT; WHIPLASH INJURIES; etc.). "Similarly, miR-138-5p, which is involved in migration, axonal growth, or in determining the size of dendritic spines, has been shown to regulate both the expression and activity of pro-apoptotic factors (i.e., Casp3, Casp7, and Bak1) following traumatic spinal cord injury." (PMID 38003699, 2023).
cancer (75 papers, 2008 to 2025). A tumor composed of atypical neoplastic, often pleomorphic cells that invade other tissues. "EGFR and BAK1 were the most prevalent genes common between ancestries, and they were shown to be linked to several types of cancers." (PMID 38398891, 2024). "EGFR, ERBB3, MMP20, MMP27, MCL1, BCL2A1 and BAK1 appear to be important genes for cancer progression due to their frequent association with recurrent cancer-related genes in women." (PMID 31205821, 2019). "BCL2 and BAK1 genes are cell death regulators and sometimes irregular patterns of the expression of these genes could reveal some underlying issues, for example, cancer." (PMID 37576599, 2023). "BAK1, a pro‐apoptotic protein, regulates cell death, possibly related to the survival of cancer cells." (PMID 39783847, 2025). "The critical mediators of intrinsic and extrinsic apoptotic signaling pathways, such as Bak1, Casp7, Bid, Bcl2, was significantly downregulated in cancer cells exposed to 5-FU." (PMID 38609535, 2024). "Up-regulation of Bak-1 and Bax of our test compounds resulted in enhanced apoptosis and cytotoxicity of cancer cells, thereby reiterating the chemical compounds’ potential to be used for cancer therapy." (PMID 37736508, 2023). "Targeted activation of Bak-1 and Bax has been investigated to stimulate apoptosis in several cancer cell lines." (PMID 37736508, 2023). "In contrast, most other genes, such as transcriptional factor ETS1 and apoptotic gene BAK1, were differentially expressed and clinically significant only in specific cancer types." (PMID 37345032, 2023). "BAK1 is an important cell death regulator that can initiate mitochondria-mediated apoptosis and is reportedly correlated with the occurrence of several cancers." (PMID 34497633, 2021). "Bcl2 forms a complex with Bad, leading to inhibition of Bcl2, which causes Bax and Bak1 to translocate to the mitochondria and contribute to apoptosis; however, we did not see a significant decrease in BCL2 expression in the A549 cancer stem cells." (PMID 34832951, 2021). "Recent studies have shown that BAK1 was regulated by miR-125b in cancer cells and neural crest cells." (PMID 34238204, 2021). "Mechanistically, HDACi induce an upregulation of cell cycle arrest and pro-apoptotic genes (CDNK1A, APAF1, PUMA, BAK1) and repression of prosurvival genes such as survivin which is in accordance with literature data for different types of cancer." (PMID 31234549, 2019). "Taken together, these results suggest that miR-125b overexpression regulates pharmacoresistance in NPM-ALK(+) cancer cells by protecting against apoptosis through BAK1 suppression." (PMID 29581862, 2018). "The BCL2 antagonist/killer 1 (Bak1) protein is upregulated in the progression of apoptosis in normal cells; in drug resistant cancers, however, it is observed that there is Bak1 suppression through miR-125b binding." (PMID 29164055, 2017). "In a further study of the possible mechanism underlying plasma-induced cancer cell apoptosis at 24 h, we determined the mRNA gene expressions of Bcl-2, BAX, BAK1 and H2AX by real time quantitative PCR analysis." (PMID 25715710, 2015). "Notably, beyond OSCC, analysis of RNA-seq data from 33 tumor projects in the TCGA revealed that BAK1 expression is significantly upregulated in malignant tumors including BLCA, UCEC, and LUSC." (PMID 40951345, 2025). "Most studies link BAK1 as well as BCL2 with the regulation of cancer." (PMID 37576599, 2023). "Among them, apoptosis-related genes, such as Casp6, Bak1 and Casp8 are up-regulated, suggesting that the GOD@POMs + laser treatment could cause cancer cells apoptosis." (PMID 36435848, 2022).
cancer (continued). "The results indicated that multiple genes and transcriptional factors related to cancer apoptosis and progression, such as Bak1, Bcl-2, KLF13 and STAT3, might be the target genes of miR-125b." (PMID 28176874, 2017). "Our results showed that the expression of these genes increased by 3.6 to 3.9 fold and 2.2 to 2.5 fold with regard to BAX and BAK1, respectively, whereas the Bcl-2 level decreased by 0.4 to 0.8 fold i.e., significant (p < 0.05), as compared to β-actin in both cancer cells." (PMID 25715710, 2015). "Generally, BAK1 was downregulated in many cancers under the influence of miRNA." (PMID 25186767, 2014). "BAK1 and BCL2L1 are key players in the regulation of apoptosis, a process often disrupted in cancer cells to evade cell death." (PMID 40869429, 2025). "BAK1 and BAX proteins play fundamental roles in apoptosis and seem to interact with VDAC proteins, whose expressions have been markedly altered in cancer, impacting their prognosis." (PMID 39449743, 2024). "miR-410 negatively regulates Bcl2 antagonist killer 1 (BAK1), Centrin 3 (CETN3) and Bromodomain containing protein 7 (BRD7) to promote other cancers." (PMID 38201476, 2023). "Bcl-2 homologous antagonist/killer (BAK1), a pro-apoptotic factor, has been identified to play crucial roles in the apoptotic process of human cancer cells or mitochondrial cells in response to various stimulations." (PMID 34238204, 2021). "According to the top 10 signal pathway based on GSEA analysis, we found BAK1 and CSE1L also played positively role in signaling pathway which is relatively correlation with HCC including pathway in cancer." (PMID 33680905, 2020). "BCL2 antagonist/killer 1 (BAK1) is an important cell death regulator, and circ0051443 can be packaged from normal cells to HCC cells by exosomes and suppress the proliferation and migration of cancer cells via the miR-331-3p/BAK1 pathway." (PMID 37154831, 2023). "However, there was no significant (p < 0.05) difference in Bak1 gene expressed in both types of cancer cells MCF-7 and MDA-MB-231 cells." (PMID 30728391, 2019). "CBD also led to a significant increase in the expression of pro-apoptotic BAK1, BAX, and BAD in the non-adherent A549 cells, supporting a role for intrinsic mitochondrial apoptosis in cancer stem cells in response to CBD, as reported by others in cancer cells." (PMID 34832951, 2021).
tumor (74 papers, 2004 to 2025). "The underlying mechanism involves the downregulation of Bak1 mRNA and protein levels within tumor tissues by miR-103a-3p." (PMID 38298209, 2024). "By interacting with miRNA-125 family members, BAK1 forms part of a regulatory pathway related to tumor growth 86,87." (PMID 40535818, 2025). "To further elucidate the molecular mechanism underlying the effect of ailanthone against HCC in vivo, we performed IHC analysis to investigate the protein expression of LC3, PINK1, PRKN, BAX, and BAK1 in tumour tissues." (PMID 39723259, 2024). "Both, proapoptotic BCL-2 or MAP kinase pathway members (BIK, BAK1, MAP3K12, and MAPK9) and proliferation-associated tumor drivers (FOS, HOXA3, and POLR2B) had an increased gene expression." (PMID 35778418, 2022). "BAK1 gene knockout can significantly inhibit proliferation and promote apoptosis of tumor cells in HCC." (PMID 35047095, 2022). "For example, in humans, multiple tumours mutations and deletions occur at higher frequency in BAX and BAK1,14, 51, 52, 53 but mRNA upregulation serves as the main mechanism of BAX and BAK1 activation in gynaecologic cancer." (PMID 32419250, 2020). "One of these genes was associated with mitochondrial fission (fission 1, or FIS1), one with apoptosis (bcl-2 homologous antagonist killer, or BAK1) and one with tumor suppression (stratifin, or SFN)." (PMID 30404157, 2018). "However, functional studies utilizing AMO-miR-103a-3p have shown that elevating Bak1 expression enhances sensitivity to cisplatin and promotes apoptosis in tumor cells." (PMID 38298209, 2024). "Furthermore, the results of the validation cohorts showed that the expression of BAK1 was upregulated in the tumor samples compared to the normal samples." (PMID 36769187, 2023). "Results showed that the selected AGs in our risk model (BAK1, DKK1, and MIF) were negatively related to the infiltration levels of tumor-infiltrating lymphocytes (including T cells, B cells, and macrophages), suggesting a low immunosuppressive activity for HNSCC patients of the high-risk groups." (PMID 35619896, 2022). "In addition, miR-103a-3p decreased the mRNA expression of Bak1 in tumor tissues, while AMO-miR-103a-3p showed the opposite effect." (PMID 33999859, 2021). "Previous studied have depicted that BAK1 played a role in tumor growth and drug sensitivity." (PMID 30988345, 2019). "Furthermore, the co-administration of Bak1 or Casp8 siRNA and the Her2/neu DNA vaccine significantly reduced tumor progression in a spontaneous mouse mammary tumor model." (PMID 30658461, 2019). "Compared with normal tissues, BAK1 and GSDME levels were markedly elevated in HCC tumor tissues, meanwhile, the expression of the NLRP6 showed the opposite trend as decreasing in HCC tumor samples in contrast with normal samples." (PMID 37149620, 2023). "Six key genes were located within malignant tumor cells and enriched predominantly in the cytoplasm of tumor cells, including PERP, BAK1, VDAC1, FOXO3, AKT3, and IGF1." (PMID 36900213, 2023). "BAK (BAK1) protein is one of the important pro-apoptotic molecules needed for PCD and apoptosis induction in tumor cells." (PMID 36186792, 2022).
tumor (continued). "miR-125b targets multiple genes involved in the regulation of apoptosis, including BAK1 and STAT3, but depending on the cell type, miR-125b can either contribute to oncogenesis or tumor suppression." (PMID 35898539, 2022). "Based on the hazard ratio (HR), the downregulated PLCG1, CASP6, CASP4, and AIM2 were considered tumor suppressors, whereas the upregulated PRKACA, NLRP9, and BAK1 were regarded as oncogenes." (PMID 34805183, 2021). "By contrast, restoration of miRNA targeting BAK1, BIM, or PTEN for cardiomyocyte protection promotes survival of tumor cells." (PMID 25364765, 2014). "mRNA expression of the candidate genes MEIS1, LDOC1, AGTR1, BAK1, TYMS and DTL were analyzed in 3 cell lines (Hep2, KB and SCC 084), 1 primary HNSCC tumor and 3 normal head and neck tissue samples." (PMID 25186767, 2014). "miR-125b-5p targets multiple genes involved in the regulation of apoptosis including BAK1, BCL3, PUMA and STAT3, but depending on the cell type, miR-125b-5p contributes either to oncogenesis or to tumor suppression." (PMID 23527180, 2013). "In these tumor tissue, most pyroptosis-related molecules, particularly IRF1, GZMB, CASP5, BAK1 and AIM2, were consistently inhibited in the cell cycle, DNA damage response, hormone AR and RTK signaling pathway, but highly activated in the apoptosis signaling way." (PMID 36437960, 2022). "Moreover, several tumor suppressors, including BTG2, TUSC1, BAK1, LATS2, FZD6 and PPP2R1B, were regarded as common targets of TET3." (PMID 32209730, 2020). "Furthermore, we identified tumour suppressors, including BTG2, TUSC1, BAK1, LATS2, FZD6 and PPP2R1B, as common targets of TLX and TET3." (PMID 26838672, 2016). "Furthermore, upon treating various types of tumour cell lines with FOXO1 inhibitors, we observed not only the upregulation of VEGFC, PD‐L1 and CCL4 but also varying degrees of increase in MOMP‐related molecules (such as BAX, BAK1, CASP3, STING, IRF3 and RELB)." (PMID 38899748, 2024). "Additionally, knockdown of pyroptosis-related gene BAK1 expression could inhibit HCC cell proliferation and promote tumor cell apoptosis." (PMID 35573678, 2022). "Interaction network results revealed that BAK1, NLRP1, CHMP7, and RIPK1 genes could interact with immune factors, including TNF-α, suggesting their influence on the immune microenvironment of the HNSCC tumor." (PMID 36246601, 2022). "Another interesting finding in our results is that the four prognostic PRGs (BAK1, CYCS, HMGB1, and NLRP1) were significantly correlated with immune cell infiltration, which further confirmed that pyroptosis in immune cells might participate in regulating the tumour microenvironment." (PMID 37337018, 2023).